TP73 (tumor protein p73)
Diseases named in the same sentence as TP73 in open-access papers (continued):
Sharing a sentence is not in itself a finding about the gene and the disease.
tumor (continued). "In harmony with this conclusion NOVA1, SLC16A3, SLC2A8, and TP73 were assigned to the essential category by De Kegel and Ryan, 2019 in less than 10% of the 558 tumor cell lines tested." (PMID 33427197, 2021). "Our results showed that CASC7 acted as a sponge of miR-34a-5p to upregulate the expression of tumor-suppressive TP73, and thereby inhibited PTC cell proliferation and migration and induced PTC cell apoptosis." (PMID 33706708, 2021). "TP73 can be translated into different isoforms with opposite functions; in particular, the A isoform (TAp73) shows tumor-suppressor activity, while the Dominant-Negative isoform (ΔNTP73) fails to induce apoptosis and cell cycle arrest." (PMID 34987311, 2021). "Many of these mediators (e.g. MMP23D, TP73, ROCK2, USF3) have been implicated in tumorigenesis and tumor suppression or progression pathways." (PMID 33684137, 2021). "Due to the usage of two different promoters, TP73 is transcribed as two isoforms, the full-length TAp73 isoforms that exhibit tumor suppressor activity and the N-terminally truncated ΔNp73 isoforms that exhibit oncogenic activity." (PMID 34204113, 2021). "Ex2 + 4G > A genotypes of TP73 are significant predictors for tumor response, tumor resectability and overall survival in PDAC." (PMID 33748108, 2021). "The molecule we chose to target is ITCH, the E3 ubiquitin ligase responsible for the degradation of a panel of tumour suppressor genes, including TP73." (PMID 31974512, 2020). "TP73 shows tumour suppressive activities through its ability to bind transcriptional target genes involved in apoptosis." (PMID 31974512, 2020). "The E3 ubiquitin ligase, ITCH, negatively regulates the tumour suppressor protein TP73, providing a therapeutic target to enhance the sensitivity of the tumour cells to the treatment." (PMID 31974512, 2020). "The up-regulated genes were associated with apoptosis induction (BTG2, TP73 and PIDD1) and cell cycle arrest (RPRM and CDNK1A), consistent with the tumor suppressive function of PKNOX2." (PMID 30745575, 2019). "We used TCGA database to analyze differential expression of TP73 between adjacent normal and tumor tissues." (PMID 31090204, 2019). "Among these tissues, TP73 expression was significantly different (P = 1.31 × 10−14) in paired tumor tissues and adjacent normal tissues." (PMID 31090204, 2019). "TP73 mRNA was significantly overexpressed in tumor tissues compared to adjacent normal tissues (P = 2.36 × 10−19)." (PMID 31090204, 2019). "Genes that were downregulated and hypermethylated in ADCs were squamous markers such as DSC3 and KRT5, as well as transcription factors such as FOXE1 and TP73, whose isoforms have demonstrated both tumor suppressor and oncogenic properties." (PMID 28787442, 2017). "The two identified homologues, TP63 and TP73, have also been related to apoptosis, and a possible role as tumor suppressors has been suggested." (PMID 25033876, 2014). "We found that TP73 had three differentially methylated CpGs, two of which were hypomethylated in the tumor tissues and located near the TSS of its shorter isoforms." (PMID 22768131, 2012). "In the TP73 gene, the hypermethylated CpG site in the tumor sample was located upstream of the TSS of the full-length mRNA isoform." (PMID 22768131, 2012). "In view of the potential relevance of Tp73 to tumorigenesis, the expression status of the gene has been addressed in various tumour types." (PMID 17047653, 2006).
tumor (continued). "In OTs, promoter hypermethylation of TP73 is detectable in 8–24% of tumours and anaplastic tumours are more common to harbour such aberration." (PMID 15475940, 2004). "When transcript levels were examined, TP73 was found to be overexpressed in a variety of tumours, but its expression is reduced or absent in certain haematological malignancies." (PMID 15475940, 2004). "The differential analysis between quartile 1 (Q1; low TP73 expression) and quartile 4 (Q4; high TP73 mRNA expression) identified 1243 genes expressed at higher levels and 1324 genes expressed at lower levels in high-TP73 tumours (Q4, log2 fold change ≥ 1 and FDR p-value < 0.05)." (PMID 40244040, 2025). "TP73 participates in complex regulatory networks that influence tumour progression." (PMID 41153767, 2025). "In this regard, hijacking of TP73‐regulated neurodevelopmental programs, including neural stemness, in TAp73‐expressing tumors, might increase tumor progression and metastatic competence." (PMID 39090849, 2025). "Interestingly, HOX genes were differentially expressed in high-TP73 tumours, with HOXA genes expressed at lower levels and HOXC and D genes expressed at higher levels." (PMID 40244040, 2025). "TP73 is rarely mutated but frequently found to be upregulated in human cancers, indicating that p73 is not a classic Knudson-type tumor suppressor." (PMID 37650871, 2023). "This leads to the effect in which the upregulation of MCL1 in these cancers not only suppresses the traditional Bcl-2 family regulation of apoptosis, but also suppresses the specific upregulation of TP73 and the resulting anti-tumor effects of these platinum-based compounds." (PMID 37760451, 2023). "FDX1 may modulate TP73 tumor suppressor through IRP2 to regulate tumor suppression, and FDX1 may be a gene related to KIRC." (PMID 36531222, 2022). "In addition, the TP73-including model revealed Residual Tumor (RT) >2 cm as an independent factor worsening drug response, while overexpression of the NAV1 gene was associated with the lower chance of CR in the same group of patients." (PMID 35867729, 2022). "Regarding CNAs, the main affected genes in this series of primary MN that recurred are located on chromosomes 22q (TIMP3), 1p (TP73), 6q (ESR1 and PARK2), and 18q (BCL2); the association among these chromosomes’ alterations and tumor recurrence has been previously demonstrated." (PMID 36011000, 2022). "Taken Tumor Associated Macrophage (TAM) as an example, the expression of TP73 was significantly positively correlated with a surface marker of TAM—chemokine factor CCL2 (r =0.148, P < 0.001), and another surface marker of TAM—cytokine IL10 (r =0.134, P = 0.003)." (PMID 35756491, 2022). "However, TP73 was positively correlated with the tumor purity of HNSC according to the immune score (r =0.163, P < 0.001)." (PMID 35756491, 2022).
tumor (continued). "Besides, our analytical results reconfirmed that TP73 expression was strongly related to tumor grade (p < 0.05)." (PMID 34121368, 2021). "Yet, the tumor suppressor function of p73 (tp73) is often attenuated in human cancers." (PMID 34445220, 2021). "The TP73 alteration identified in ATLL may act as an oncogene because it lacks a transactivation domain, which is required for TP73 to act as a tumor suppressor." (PMID 33918793, 2021). "Abundant studies have characterized TP73 as a tumor-suppressive gene." (PMID 33706708, 2021). "We further distinguished CGGA_325 and CGGA_693 datasets by tumor grade, and the correlation analysis found that TP73 expression was significantly correlated with the status of 1p/19q codeletion regardless of tumor grade (p < 0.05), except for CGGA_693 grade II subgroup (p = 0.8715)." (PMID 34121368, 2021). "The activity of the so-called “tumor suppressor” TP73/p73 converges on TSC1-TSC2." (PMID 31766386, 2019). "TP73 is a known tumor suppressor, and its methylation could contribute to reduced apoptosis in response to chemo- or radiotherapy relative to SCCs." (PMID 28787442, 2017). "Other lncRNAs lie in proximity of genes already known in cancer and thus potentially involved in their regulation, for example lnc-LRRC47-1, which may regulate the tumor suppressor TP73 gene." (PMID 26895470, 2016). "Remarkably, several groups, including ours, have recently demonstrated that TP73 plays a fundamental role in angiogenesis regulation and that differential expression of TP73 could have important consequences in tumor angiogenesis." (PMID 27308533, 2016). "However, this series of cases has been studied in detail as to their copy-number status at 1p36 and this has shown that the majority of the tumours have two copies of TP73." (PMID 18781178, 2008). "Others have reported higher TP73 expression in human tumor tissue than in normal brain tissue." (PMID 17626635, 2007). "In addition, subsequent research could include the establishment of a subcutaneous tumor model in rats in order to examine the role of TP73 in the proliferation and migration of tumors in vivo." (PMID 35756491, 2022). "In addition, mutations in CREBBP, EP300, TP73, RBL1, RBL2 and NOTCH family genes are largely mutually exclusive, suggesting that they may play similar tumor-promoting roles in the onset of SCLC." (PMID 34168983, 2021). "However, the extremely low frequency of the TP73 gene mutations in cancer and initial experiments on Trp73−/−-mice failed to support its potential tumor suppressor role." (PMID 34207603, 2021). "Likewise, MGMT and TP73 exhibit hypomethylation in multiple tumor types." (PMID 23033966, 2012). "Several tumor-specific TFs were detected within the ED and SED, including TP63, FOSL1, JUND, GRHL2, SNAI2, KLF5, TP73, and SMAD3." (PMID 41323280, 2025).
tumor (continued). "Due to the pivotal roles of EPGN, LCN10, and TP73 in the TIME, we conducted an analysis of immune cell profiles in CESC to investigate the connection between IRGPI and the composition of tumor-infiltrating immune cells." (PMID 38933923, 2024). "Of the 11 neoplasm-related genes in these subclusters, the expression of six (ANGPT2, TP73, NOVA1, CDH11, CXCL12, and LAMA1) were significantly repressed in KRT and one (EPHA2) was higher expressed in KRT compared with IMU." (PMID 37654626, 2023). "Therefore, TP73 may suppress or promote tumor growth in different kinds of cancers." (PMID 35756491, 2022). "In this study, we systematically assessed the prognostic performance of DNA replication-related genes for predicting tumor recurrence and constructed a novel and robust signature including EREG, KCTD13, MCM3AP, MCM3, POLD2, TERF2, and TP73." (PMID 33748108, 2021). "For example, one finding shows that TP63, TP73, and SOX2 expression in tumor tissues of early, middle, and late stages is higher than that in the adjacent non-tumorous tissues." (PMID 29340250, 2018). "All five of the identified genes (DLK1, PLAGL1, SLC22A18, TP73, and WT1) have presumed tumor suppressing functions and taken together demonstrate a strong tendency towards higher methylation at the CpG sites assessed." (PMID 23890537, 2013). "In contrast, ENST00000378295 TP73 transcripts were significantly lower in non-malignant breast specimens relative to primary tumours." (PMID 41153767, 2025). "Furthermore, we have validated the identified RNA editing sites using matched RNA and genome DNA samples derived from the same tumor biopsies by Sanger sequencing and cloning in selected genes (CARD11 and TP73)." (PMID 37255666, 2023). "YAP1 binds to TEADs to facilitate the expression of tumor-promoting genes, and YAP1 may switch to bind to TP73 to promote apoptosis of cancer cells." (PMID 36479120, 2022).
tumor (continued). "For example, we found that ATAD1, TBC1D9, and TNNC2 expression are all mediated by transcription factors ACTRT2, MMP23B, and TP73 and methylation sites around MMP23B and TP73; these transcription factors have known functions in tumor suppression or proliferation." (PMID 33684137, 2021). "Moreover, after addition of tumor purity into the multivariate model, only PRPF19 (P = .005‐.04, c‐index = 0.71‐0.73) and TP73 (P = .02‐.04, c‐index = 0.71‐0.72) methylation were significantly associated with better OS and PFS." (PMID 32991787, 2020). "Eleven cancer related genes were found to have methylation (defined as more than 10 % methylation) in at least some of the tumours: RASSF1A (64 %), TWIST1 (61 %), CDH13 (51 %), APC (50 %), MAL (35 %), GSTP1 (30 %), WIF1 (26 %), RARβ (19 %), BRCA1 (2 %), CDKN2A (2 %) and TP73 (2 %)." (PMID 26452468, 2015). "and TP73 mRNA expression in tumor grade 1 was significantly higher than non-cancerous tissues." (PMID 34778250, 2021). "One significant player in tumor progression, TP73 tumor suppressor gene, could not be left out of tumor progression." (PMID 34842635, 2021). "Moreover, DK1 also enhanced the expression of several other tumor suppressor genes that are related to this pathway such as FOXO, TP73, CDKN1A, Caspase, CYCS, and GADD45A while impeded the expression of other proto-oncogenes namely PIK3R3, BCL-2, IGFBP2, HGF, and FGF." (PMID 34204873, 2021). "However, to date, no studies have demonstrated that USP28 stabilizes the tumor suppressors Tp73 or Tap63." (PMID 34685632, 2021). "This suggested that other TP73-independent mechanisms may also be involved in ITCH-mediated tumor cell apoptosis, because TP73 is not the sole protein regulated by ITCH." (PMID 31974512, 2020). "Given the number of mutations and the nature of the mutations found, including at least one tumor suppressor gene, TP73, and several genes that may be associated with other types of malignancy (ATM, CDH5, MAGED1), WDPM clearly appears to be a functionally benign neoplasm and not a reactive process." (PMID 32545767, 2020).